FABP4 (fatty acid binding protein 4)
Diseases named in the same sentence as FABP4 in open-access papers (continued):
Sharing a sentence is not in itself a finding about the gene and the disease.
cancer (continued). "Therefore, we speculated that FABP4 is not only linked to both cellular and systemic metabolic processes but also probably as a clinical or biologic marker associated with the outcome of cancers, especially in NB." (PMID 33931964, 2021). "Evidence suggests that FABP4 levels impact diseases ranging from metabolic syndrome, type two diabetes, atherosclerosis and various forms of cancer including breast, liver, colon, and ovarian." (PMID 34572888, 2021). "It is worth mentioning that the FABP4 inhibitor significantly increased the sensitivity of cancer cells to carboplatin." (PMID 33809784, 2021). "Consistently, during BC progression, in cancer cells there is an increase of FABP4 and of lipogenic enzymes, like fatty acid synthase (FASN)." (PMID 32850459, 2020). "FABP4 is regarded as a critical factor modulating interaction between cancer cells and peritumoral adipocytes." (PMID 33352874, 2020). "A previous study reported that FABP4 promotes HGSOC progression by mediating lipid metabolism in cancer cells." (PMID 32224886, 2020). "The importance of FABP4 in facilitating the transport of fatty acids from adipocytes to cancer cells has also been shown in ovarian and colon cancers." (PMID 32913185, 2020). "Metastatic cells elevate fatty acid binding protein 4 (FABP4) expression and secretion, which favors the uptake of fatty acid released from adipocytes to cancer cells and allows FAO to fuel proliferation." (PMID 33291682, 2020). "Fatty acid binding protein 4 (FABP4) was strongly expressed at the adipocyte–cancer cell interface and pharmacological inactivation of FABP4 decreased cancer cell lipid accumulation, invasiveness and omental metastasis." (PMID 33339340, 2020). "Adipocytes sustain cancer cell growth by activating lipolytic processes with consequent release of free FAs that are up taken by cancer cells over-expressing FABP4, which in turn release exosomes containing pro-lipolytic factors (i.e., miR-144 and miR-126)." (PMID 32486505, 2020). "Lipid mobilization between peritumoral adipocytes and cancer cells has been shown to be a requirement for metastasis in some cancers, with FABP4 playing a key role in this process." (PMID 33352874, 2020). "Free fatty acids enter into cancer cells, are transported through FABP4 and degraded to provide ATP and bioactive lipids needed for cell invasion, angiogenesis and immunosuppression." (PMID 32850459, 2020). "High MMP9 mRNA expression levels were associated with the expression of genes involved in cancer progression: BRCA2, COL4A1 and ITGA6, and were also associated with high FABP4 mRNA expression levels." (PMID 31874999, 2019). "FABP4 has been shown to play a role in cancer cell growth and metastasis in several cancers, including ovarian, breast and oral squamous carcinomas." (PMID 30575815, 2019). "Adipocytes, through fatty acid-binding protein 4 (FABP4), transferred processed fats to tumors for β-oxidation to generate energy required for carcinoma growth." (PMID 31817625, 2019). "Adipocytes co-cultured with cancer cells exhibit de-lipidation, decreased expression of adipocyte markers such as Ap2 and FABP4, increased expression of MMP11, and enhanced release of inflammation-promoting cytokines IL-6 and IL-1β." (PMID 30356678, 2018). "In the control group, the cancer cells did not invade normal organs (muscle, pancreas), however, after ectopic expression of FABP4, the cancer cells were found to be deeply invading the normal tissues." (PMID 30050129, 2018). "Previous studies have shown that FABP4 present in the stromal cells can lead to cancer progression by providing a source of energy to cancer cells or increasing angiogenesis." (PMID 30050129, 2018). "Of the factors examined, hypoxia (1% O2) consistently led to a significant increase in FABP4 expression in cancer cells at 24 and 48 h." (PMID 30050129, 2018).
cancer (continued). "Lipid transfer between adipocytes and cancer cells mediated by fatty acid binding protein 4 (FABP4), through a “symbiotic” process between cancer cells and the fatty microenvironment was described as a key regulator of peritoneal metastasis." (PMID 30103384, 2018). "We discovered that FABP4 (fatty acid binding protein) can substantially increase the metastatic potential of cancer cells." (PMID 30050129, 2018). "Epithelial FABP4 expression in low-grade and high-grade carcinomas was similar in intensity and extent." (PMID 27568980, 2017). "In vitro studies showed that cocultivation of several cancer cell lines (ovarian, breast, and colon) with adipocytes induced FABP4 mRNA expression." (PMID 26959740, 2016). "The fact that bone marrow is adipocyte-rich suggests a role for adipocytes in enhancing FABP4 expression and thereby playing an important role in cancer progression." (PMID 25866768, 2015). "For example, one report suggested that adipocytes act as an energy source for the cancer cells, and identified FABP4 up-regulation in omental metastases as compared to primary ovarian tumors." (PMID 25569080, 2015). "FAPB4 is also susceptible to the extracellular milieu as there is growing evidence that adipocytes increase FABP4 mRNA and protein expression in cancer cells." (PMID 25866768, 2015). "FABP4 has been implicated in epithelial–mesenchymal transition (EMT) through CD36 up‐regulation in glioma cells, and its inhibition can suppress adipocyte‐induced cancer cell metastasis and EMT phenotypes." (PMID 41454478, 2026). "Furthermore, cancer‐associated adipocytes (CAAs) in ILC exhibit elevated expression of hormone‐sensitive lipase (HSL) and fatty acid‐binding protein 4 (FABP4), alongside reduced perilipin A levels." (PMID 40703006, 2025). "In fact, real-time cellular metabolic analysis using a Seahorse bioanalyzer showed that pharmacological inhibition of FABP4 in HOCF by BMS309403 led to pseudohypoxic changes that may be a critical cause of neovascularization in AMD and malignant tumors." (PMID 40076418, 2025). "Research indicates that the expression FABP4 is higher in cancer cells with metastatic potential." (PMID 39823981, 2025). "This indicates a potential interaction between cancer cells and adipocytes, potentially involving the proteins FABP4 and UCP2, which may contribute to treatment resistance." (PMID 39823981, 2025). "FABP4 is involved in the intracellular transport and metabolism of fatty acids within cancer cells." (PMID 41228384, 2025). "Although a role for FABP4 in the regulation of cancer stemness has been suggested, the functional and mechanistic roles of adipose-derived FABP4 in cancer stemness remain unknown." (PMID 41392988, 2025). "These interactions could disrupt FABP4′s signaling and lipid transport functions to restrict cancer cell proliferation and growth." (PMID 40430580, 2025). "In addition, among FABP proteins, FABP4 is also expressed in macrophages, in addition to adipocytes, and plays a pivotal role in the pathogenesis of cardiovascular diseases, HT, DM, and cancer." (PMID 39062961, 2024). "Inhibition of FABP4 resulted in changes in the lipidomic profile of cancer cells." (PMID 39624081, 2024). "The pan-cancer analysis of single myeloid cells across 15 human cancer types unveiled significant findings, indicating that AMs express genes such as FABP4, MARCO, MRC1( also known as CD206), MSR1 and PPAR-γ, which are involved in self-replenishment through the secretion of (TGF-β." (PMID 38229178, 2024). "Notably, FABP4 mediated carboplatin resistance, while its inhibition increased the sensitivity of cancer cells to carboplatin, suggesting FABP4 as a therapeutic target for combination with platinum chemotherapy in patients with advanced or recurrent disease." (PMID 39624081, 2024). "FABP4 could provide fatty acids to malignant cells to maintain cell proliferation and affect cancer progression." (PMID 37950277, 2023).
cancer (continued). "Moreover, the production of IL-8 and fatty acid-binding protein 4 by adipocytes increased after co-culture of human adipocytes and ovarian cancer cells thereby promoting the homing, migration, and invasion of cancer cells." (PMID 37666813, 2023). "The released free FA can also activate and regulate other cells such as macrophages, vascular endothelial cells and muscle cells, which is conducive to the formation of the original cancer microenvironment, and FABP4 released by CAAs is an energy source carrier for cell invasion." (PMID 37666813, 2023). "FABP4 plays a critical role in the interaction between cancer cells and CAAs." (PMID 35788730, 2022). "All these recent findings related to cancer research proved that FABP4 targeting may represent an effective and promising therapeutic strategy against oncological conditions, in addition to the established effects on metabolic and cardiovascular diseases." (PMID 36355506, 2022). "Next, the potential value of FABP4 in cancer prognosis was verified by the K-M curve." (PMID 36532833, 2022). "Deregulated expression of FABP4 has been observed in multiple cancer types." (PMID 35899119, 2022). "However, the specific relationship between FABP4 and various cancers is still unclear, and the specific mechanism of FABP4 on cancer still needs to be explored." (PMID 36060264, 2022). "The expression of FABP4 is upregulated or downregulated in a variety of cancers." (PMID 36532833, 2022). "And Fabp4 plays an important role in transporting fatty acids between fat cells and cancer cells." (PMID 35783385, 2022). "FABP4 has emerged as a critical player in tumorigenesis, thus targeting FABP4 may provide a promising therapeutic target for cancer treatment." (PMID 35899119, 2022). "Additionally, FABP4 is robustly expressed in macrophages and indirectly promotes cancer progression by altering matrix metalloproteinase (MMP) activity and promoting IL6." (PMID 35740306, 2022). "Although FA can diffuse across phospholipid (PL) bilayers, much of the FA uptake is enabled by the increased expression of integral or membrane-associated proteins in cancer cells (FATP1 and CD36) or the expression of FABP4 in the TME by adipocytes and endothelial cells." (PMID 36551752, 2022). "Fatty acid binding protein (FABP4) inhibitors are of synthetic and therapeutic interest and ongoing clinical studies indicate that they may be a promise for the treatment of cancer, as well as other diseases." (PMID 36355506, 2022). "FABP4 was the most extensively investigated gene in cancer out of this list." (PMID 35198079, 2022). "Overexpression of AEBP1 and MCM4 for OB as well as of FABP4 for AD differentiation seem to be the most promising molecular targets which could be used for regenerative medicine, stem cell, and cancer research in the future." (PMID 35269711, 2022). "The CNVs of RAB7A, BIRC5, SERPINE1, and FABP4 were relatively high in most cancers." (PMID 36518255, 2022). "Taken together, these studies indicate that FABP4 may play an important and dual cancer-promoting or suppressing role in human cancers." (PMID 36264920, 2022). "Our results showed that BIRC5 was up-regulated, whereas FABP4 was down-regulated in most cancers." (PMID 36518255, 2022). "Through the K-M curve, FABP4 was found to correlate to the prognosis of various cancers." (PMID 36532833, 2022). "Therapeutic targeting of FABP4 evaluated in different cancer types." (PMID 35899119, 2022). "Similarly to that described in other cancers, FABP4 appears to be a potential target in AML, as it promotes AML aggressiveness through enhanced DNMT-1-dependent DNA methylation." (PMID 33498240, 2021). "This might be due to the heterogeneity among different cancers, and understanding why FABP4 plays a different role in various cancers requires further research." (PMID 34702269, 2021).
cancer (continued). "The increased FABP4 expression in this study corroborates several studies, which have linked increased FABP4 expression to poor prognosis in several cancers, without any specific link to CD3629–31." (PMID 34561446, 2021). "The experiments on mice proved the role of FABP4 in the metastatic potential of cancer cells." (PMID 33809784, 2021). "Among all cancer tissues, we found that moderately to poorly differentiated and advanced FIGO stage CCa tissues had higher levels of FABP4, demonstrating that FABP4 was associated with CCa progression." (PMID 34702269, 2021). "Results on the role of FABP4 in cancer are scarce and conflicting." (PMID 30575815, 2019). "It is possible that FABP4 concentration would be higher in patients with metabolic or cardiovascular diseases than in young healthy individuals Moreover, cancer patients would have a greater circulating FABP4 concentration." (PMID 31826012, 2019). "Moreover, this microenvironment can also enhance tumor growth by transferring FABP4 (a protein that known to regulate lipolysis) to cancer cells, which is used by the cancer cells to process fatty acid and provide cellular energy." (PMID 31366178, 2019). "Since FABP4 is a key molecule involved in free fatty acid uptake, inhibiting its ability to uptake fatty acid could be a potential therapeutic avenue to inhibit cancer metastasis." (PMID 30050129, 2018). "In our study, we investigated the expression of FABP4 at both mRNA and protein levels, and by examining 175 cases of patients with cancer of the liver tissue microarray, the significance between the expression of FABP4 and clinical characteristics had been discussed." (PMID 29733540, 2018). "Moreover, as for the mechanism of FABP4 in other various cancers 17, many studies have been reported." (PMID 29733540, 2018). "In addition, FABP4 has been reported to mediate the transfer of FAs from adipocytes into cancer cells during the cancer cell-adipocyte interaction." (PMID 29914512, 2018). "However, the origin of the high serum FABP4 levels (i.e., cancer cell origin or fat tissue origin) remains to be determined." (PMID 29340091, 2017). "However, recent studies have reported that FABP4 is highly expressed in a range of cancer cells and human tumors." (PMID 25569080, 2015). "Thus, blocking FABP4 lipid binding and secretion might represent novel strategies for preventing lipid utilization by cancer cells." (PMID 39513934, 2024). "Thus, FABP4’s critical role in cancer cell survival involves its interactions with adipocytes." (PMID 37065866, 2023). "While FABP4 levels outside of the adipocyte and macrophage and perhaps endothelial cells are generally considered to be low in the normal state, high levels of expression have been widely reported in various tissues not only in cancers but also in other types of pathological states." (PMID 37207357, 2023). "Thus, clinical trials should be accelerated to test the therapeutic effects of FABP4 inhibitors in diverse types of cancer, which may implement the options of therapeutic strategies for cancer patients in clinical practice." (PMID 35899119, 2022). "In addition, aberrant expression of FABP4 has been observed in multiple cancer types." (PMID 35899119, 2022). "In the present study, we demonstrated that elevated circulating FABP4 concentration predicts cardiovascular death, but not all-cause death or cancer death, as a hard endpoint after adjustment of confounding factors including hsCRP in a general population (Model 3 and Model 4)." (PMID 33597568, 2021). "In addition, FABP4 is also involved in the progression of various cancers." (PMID 33931964, 2021). "In addition, FABP4 present in various types of cancer cells was involved in cancer progression." (PMID 29340091, 2017). "Besides, FABP4 has also been shown to be an adipose-derived cytokine that could be released into circulation, and involved in cancer cell growth and metastasis in multiple malignancies." (PMID 29237483, 2017).
cancer (continued). "Compared to primary cancer samples, genes such as GLYATL2, EDIL3, MEG3, FABP4, ASCL1, GRP, and WDFY4 were highly upregulated in CRPC, with statistically significant differences underscoring their potential roles in driving the castration-resistant phenotype." (PMID 40165961, 2025). "In pan-cancer analyses, FABP8 forms a gene cluster with FABP4, FABP5, FABP9, and FABP12, which frequently undergo co-amplification in various cancers." (PMID 40717587, 2025). "Coculture experiments with adipocytes showed that FABP4 and UCP2 promote lipid metabolic reprogramming, facilitating cancer cell survival in a dormant state." (PMID 39823981, 2025). "Two key proteins involved in this process that are upregulated in cancer cells in close proximity to adipocytes are CD36 and fatty acid-binding protein 4 (FABP4)." (PMID 41228384, 2025). "Omental adipocytes have been shown to provide energy for proliferating EOC via the direct transfer of fatty acids to neighbouring cancer cells, while suppression of this process through inhibition of CD36 or FABP4 can sensitize EOC to chemotherapy." (PMID 39285292, 2024). "Targeting the dysregulated lipid metabolism in cancer through the inhibition of transporters CD36 and FABP4, the disruption of de novo lipogenesis, and FAO enzymes, as well as cholesterol synthesis, has revealed potential avenues for therapeutics." (PMID 38610991, 2024). "Compared with the adjacent normal tissues and cancer tissues of patients taking atorvastatin, the expressions of MMP9, MMP12, CD36, and FABP4 in LUSC tissues increased significantly." (PMID 37978381, 2023). "Furthermore, given the discovery of the protein’s role in cancer progression, the inhibition of FABP4 might offer a viable therapeutic option for cancer patients through the suppression or decrease of early-stage tumors and metastasis, and they have a possible use as biomarkers for cancer detection." (PMID 36985701, 2023). "And these AML cells can fully utilize fatty acid oxidation to activate cancer-promoting signaling pathways such as AMPK, and up-regulate genes such as PPARγ, FABP4, CD36 and BCL2 genes to promote their own survival and proliferation." (PMID 36002858, 2022). "By contrast, the FN1-related molecular pairs, including FN1-CD44 (a marker of cancer stem cells) and FN1-(ITGAV + ITGB1), were prompted between SELENOP-Mφ/SPP1-Mφ and FABP4-Mφ/FCN1-Mφ/CD4/CD8 cells in LUAD." (PMID 36008393, 2022). "Nevertheless, the roles of HOXC6, SERPINE1, FABP4, SCG2, and CALB2 in tumorigenesis, cancer immunity, and ICB treatment are poorly understood." (PMID 35836930, 2022). "GLUT1, FABPpm, MCT4 and SNAT1 genes were significantly overexpressed in carcinomas compared with controls, while expression of CD36/SR-B2, FATP1, FABP4, GLUT4, ASCT2 and LPL was decreased." (PMID 36012230, 2022). "Therefore, whether FABP4 played a role in promoting or suppressing cancer growth is controversial." (PMID 34558731, 2021). "More specifically, FABP4 was involved in regulation of lipolysis in adipocytes and CXCL12 participated in pathways in cancer and axon guidance." (PMID 34123594, 2021). "When divided into 3 groups according to tertiles of FABP4 level at baseline by sex (T1–T3), Kaplan–Meier survival curves showed that there were significant differences in rates of all-cause death and cardiovascular death, but not cancer death, among the groups." (PMID 33597568, 2021). "Our observation of a correlation between CD36 and FABP4 in a variety of cancers, and the direct interaction between CD36 and FABP4 offer a key insight to how adipocyte induce metabolic reprogramming." (PMID 34561446, 2021). "Conclusively, three key genes, LPL, FABP4 and CPT1, form the metabolic axis that regulates fatty acid production, transport and oxidization, which is essential for cancer cell activity." (PMID 34803493, 2021).